CHD3 (chromodomain helicase DNA binding protein 3)
Description:
ATP-dependent chromatin-remodeling factor that binds and distorts nucleosomal DNA. Acts as a component of the histone deacetylase NuRD complex which participates in the remodeling of chromatin. Involved in transcriptional repression as part of the NuRD complex. Required for anchoring centrosomal pericentrin in both interphase and mitosis, for spindle organization and centrosome integrity.
Synonyms: Mi-2a; ZFH; Mi2-ALPHA; SNIBCPS
Tractability: PROTAC: UniProt records ubiquitination sites on it; ubiquitination databases record sites on it; its protein half-life has been measured.
Target class: Enzyme; Hydrolase
Gene: Protein-coding gene on chromosome 17 (7,884,796 to 7,912,760, forward strand). Ensembl gene ENSG00000170004.
Subcellular location: Nucleus, PML body; Nucleus; Cytoplasm, cytoskeleton, microtubule organizing center, centrosome
Subcellular location (Human Protein Atlas): Nucleoli; Nucleoplasm; Centriolar satellite
Pathways (Reactome):
Gene expression (Transcription): ERCC6 (CSB) and EHMT2 (G9a) positively regulate rRNA expression; RNA Polymerase I Transcription Initiation; Regulation of endogenous retroelements by KRAB-ZFP proteins; Regulation of endogenous retroelements by Piwi-interacting RNAs (piRNAs)
Chromatin organization: HDACs deacetylate histones; Interaction of NuRD complexes with transcription factors; NuRD complex assembly
Developmental Biology: Differentiation of naive CD4+ T cells to T helper 2 cells (Th2 cells); Transcriptional regulation of brown and beige adipocyte differentiation by EBF2
Disease: Potential therapeutics for SARS
Metabolism of proteins: SUMOylation of chromatin organization proteins
Signal Transduction: Regulation of PTEN gene transcription
Gene Ontology:
Molecular function: ATP hydrolysis activity; ATP-dependent chromatin remodeler activity; protein binding; RNA binding; transcription cis-regulatory region binding; chromatin binding; DNA binding; helicase activity; histone binding; zinc ion binding; ATP binding
Biological process: centrosome cycle; chromatin remodeling; negative regulation of transcription by RNA polymerase II; spindle organization; negative regulation of DNA-templated transcription; positive regulation of DNA-templated transcription; regulation of cell fate specification; regulation of DNA-templated transcription; regulation of stem cell differentiation
Cellular component: centrosome; cytoplasm; nucleolus; nucleoplasm; nucleus; NuRD complex; PML body; chromatin
Genetic constraint (gnomAD): Loss-of-function variants: 51 observed, 250.3 expected, observed/expected ratio (o/e) 0.2, 90% interval 0.16 to 0.26. The upper end of that interval is the gene's LOEUF score, 0.26, which puts it in group 1 of 6, group 1 being the genes least tolerant of losing a copy. Missense variants: 1,459 observed, 2,646 expected, observed/expected ratio (o/e) 0.55, 90% interval 0.53 to 0.58. Synonymous variants: 977 observed, 1,006.5 expected, observed/expected ratio (o/e) 0.97, 90% interval 0.92 to 1.02.
Gene-disease validity (ClinGen):
ClinGen rates the evidence that CHD3 causes each of these diseases.
Snijders Blok-Campeau syndrome (autosomal dominant): Definitive. Snijders Blok-Campeau syndrome (SNIBCPS) is an autosomal dominant neurodevelopmental disorder characterized by global developmental delay with impaired intellectual development and delayed speech acquisition.
Homologues: Orthologues: chimpanzee CHD3 (99% identical), macaque CHD3 (98% identical), dog CHD3 (98% identical), pig CHD3 (97% identical), guinea pig CHD3 (97% identical), mouse Chd3 (96% identical), rabbit CHD3 (94% identical), rat Chd3 (91% identical), tropical clawed frog chd3 (77% identical), zebrafish chd3 (73% identical). Paralogues in human: CHD5 (68% identical), CHD4 (66% identical), CHD7 (23% identical), CHD9 (22% identical), CHD6 (21% identical), CHD8 (21% identical), CHD2 (21% identical), CHD1 (20% identical), SMARCA4 (17% identical), SMARCA2 (16% identical), SRCAP (16% identical), EP400 (15% identical), and 18 more.
Diseases named in the same sentence as CHD3 in open-access papers:
CHD3 is named in the same sentence as 72 diseases in open-access papers, as found by Europe PMC text mining. Sharing a sentence is not in itself a finding about the gene and the disease. The quoted sentences say what the papers report.
Snijders Blok-Campeau syndrome (8 papers, 2021 to 2025). "Pathogenic genetic variants in the NuRD component CHD3 cause Snijders Blok-Campeau Syndrome, a neurodevelopmental disorder manifesting with intellectual disability and craniofacial anomalies." (PMID 40835974, 2025). "It is worth noting that two intragenic suppressor mutations, G827R and D986D, correspond to residues that are mutated in Snijders Blok-Campeau syndrome (G961 and D1120 in human CHD3)." (PMID 37938928, 2024). "Specifically, CHD3 mutations cause Snijders Blok–Campeau syndrome, which is frequently characterized by autism and signs of connective tissue laxity." (PMID 33944996, 2021). "In addition, the PubMed database was searched using the keywords “Snijders Blok-Campeau syndrome,” “CHD3,” or “SNIBCPS” to summarize the gene mutations and clinical phenotypic characteristics of children with SNIBCPS." (PMID 39050258, 2024). "Further studies may help to elucidate genotype–phenotype correlations and to understand the mechanism by which a CHD3 gene defect causes Snijders Blok–Campeau syndrome (OMIM #518205)." (PMID 37761804, 2023). "Snijders Blok-Campeau Syndrome (SNIBCPS, OMIM# 618205) is a rare neurodevelopmental disorder caused by mutations in the Chromodomain Helicase DNA Binding Protein 3 (CHD3) gene." (PMID 40881826, 2025). "Snijders Blok-Campeau syndrome (SNIBCPS) is a rare genetic disorder characterized by facial abnormalities, hypotonia, macrocephaly, and global developmental delay (GDD) caused by mutations in CHD3 gene." (PMID 39050258, 2024). "Pathogenic variants in CHD proteins contribute to the development of a range of neurological disorders, such as CHD1 in Pilarowski-Bjornsson syndrome, CHD3 in Snijders Blok-Campeau syndrome (SNIBCPS), CHD4 in Sifram-Hitz-Weiss syndrome, CHD7 and CHD8 in Autism Spectrum Disorder (ASD)." (PMID 36647159, 2023).
breast carcinoma (7 papers, 2016 to 2025). "CHD3 encodes a chromatin-remodeling factor to repress transcription and is involved in breast cancer." (PMID 29262625, 2017). "We found that CHD7 was the most commonly gained/amplified and mutated, whereas CHD3 was the most deleted across the majority of tumor types, including breast cancer." (PMID 28649742, 2017). "Here, we focused on analyzing the mutation spectrum of ASXL1-3 and CHD3-5 genes in breast cancer." (PMID 28055972, 2017). "Other genes associating with this component were CHD3 in bladder cancer, HERC2 in ovary cancer, PIK3C2B in lung squamous cell cancer, EP300 in skin cancer (and breast cancer at a FDR of 2%), RBBP5 in pan-cancer, and SMC1B in pan-cancer." (PMID 35764656, 2022). "In contrast, the most deleted gene, PHF23, had the highest frequency (43.48%) of mRNA underexpression (Z-score < -1), and CHD3 was underexpressed in 35.14% of TCGA breast cancer samples." (PMID 28055972, 2017). "We previously reported that CHD3 and CHD4 are commonly mutated in a subset of breast cancers." (PMID 28649742, 2017). "Furthermore, CHD7 was overexpressed (Z‐score ≥ 1) in 33.96% and CHD3 was underexpressed (Z‐score ≤ −1) in 35.1% of TCGA breast cancers." (PMID 28649742, 2017). "Similar to TOP1, increased CHD3 expression was associated with BRCA1/2-related breast carcinoma, independent of TNBC and age." (PMID 27566577, 2016). "Non-functional studies:CHD3 showed heterozygous loss in approximately 60% of breast cancer." (PMID 41278204, 2025). "While CHD3 is considered as an oncogene and CHD4 a tumor suppressor, recent evidence demonstrates the role of CHD4 as an oncogene in breast cancers, as its amplifications are more common." (PMID 41278204, 2025). "CHD3 and CHD9 are the most deleted CHD genes in breast cancer, with 60% and 55% of breast cancer patients showing heterozygous loss, respectively." (PMID 41278204, 2025). "In contrast to CHD3, the expression level of CHD4 was higher in Luminal, HER2+, and basal-like breast cancer compared with normal-like breast cancers." (PMID 28055972, 2017). "By conducting integrated genomic and transcriptomic analyses of breast cancers with different molecular subtypes and clinicopathological features, we identified a subset of PHF genes, including PGYO2, CHD3, and ZMYND8, that have high frequencies of CNA and altered mRNA expression." (PMID 28055972, 2017).
Intellectual disability (5 papers, 2018 to 2025). "Pathogenic variants of CHD3 are primarily associated with disruption of enzyme function, and neurodevelopmental disorders manifest as macrocephaly and intellectual disability." (PMID 39050258, 2024). "We implicate de novo CHD3 mutations in a syndrome characterized by intellectual disability, macrocephaly, and impaired speech and language." (PMID 30397230, 2018). "The characteristic phenotype of individuals with CHD3 mutations overlaps with that reported for de novo mutations in CHD4, in which intellectual disability, macrocephaly, ventriculomegaly, undescended testes, and similar facial features have been reported." (PMID 30397230, 2018). "Finally, pathogenic variants in CHD3 and CHD4 have recently been described in patients with developmental delay, intellectual disability, macrocephaly, impaired speech, and dysmorphic features." (PMID 33944996, 2021). "Since there is no specific treatment for CHD3-related intellectual disability, management is primarily supportive and involves early intervention with speech, physical, and occupational therapies, as well as educational support and management of associated medical issues." (PMID 40881826, 2025).
epilepsy (3 papers, 2020 to 2025). A brain disorder characterized by episodes of abnormally increased neuronal discharge resulting in transient episodes of sensory or motor neurological dysfunction, or psychic dysfunction. "Previously, CHD3 gene variants causing epilepsy are rare and only 1 case has been reported." (PMID 40527848, 2025). "Pathogenic variants in genes, such as PGAP3, CHD3, and SMAD6, can impair motor and cognitive performance without producing major neurological symptoms like epilepsy, suggesting that these deficits arise from developmental or structural abnormalities rather than from direct neurodegeneration." (PMID 41300846, 2025). "Additionally, four of the brain-expressed, constrained genes that we identified through the new paralog conservation test and presented in the first pre-print version of the manuscript, CHD3, CACNA1E, PHIP, and GABRB2, were recently shown to be significantly enriched in NDDs with epilepsy." (PMID 32183904, 2020).
ovarian cancer (3 papers, 2017 to 2025). A primary or metastatic malignant neoplasm involving the ovary. "In ovarian cancer, YBX1 recognizes m5C-modified CHD3 mRNA and maintains its stability by recruiting the RNA-binding protein PABPC1, thereby enhancing homologous recombination (HR) repair and promoting resistance to platinum-induced apoptosis." (PMID 40819060, 2025). "Among 32 tumor types, CHD7 was more frequently (> 50%) amplified/gained in 11 tumor types, including breast, lung, colorectal, and ovarian cancers, and CHD6 was more frequently (> 50%) amplified/gained in eight TCGA tumor types, whereas CHD3 was more frequently deleted (> 50%) in nine tumor types." (PMID 28649742, 2017).
acute myeloid leukemia (2 papers, 2017 to 2018). Acute myeloid leukemia (AML) is a group of neoplasms arising from precursor cells committed to the myeloid cell-line differentiation. "Some of these genes have already been shown to play a role in hematologic malignancies, including CLL (Pim-2, Met, Rgs16, Ccdc88a, Zcchc18, Clip3), diffuse large B cell lymphoma, follicular lymphoma (Vav3), acute lymphoblastic leukemia (ALL) (Itm2a, Chst1) or acute myeloid leukemia (AML) (Chd3)." (PMID 30271400, 2018).
apraxia (2 papers, 2025). Apraxia is a neurological disorder characterized by the inability to perform tasks or movements, despite having the desire and physical ability to perform them. "Moreover, CHD3 protein interacts with FOXP2, which is known to be implicated in language problems in Childhood Apraxia of Speech." (PMID 40881826, 2025).
colon carcinoma (2 papers, 2023). "The most specific loci were in the exons of genes JAK1 and CHD3 (for endometrial cancer); BMPR2, ELAV3, GLYR1, and ZNF43 (for colon cancer); and XYLT2 (for stomach cancer)." (PMID 37894432, 2023).
latent infection (2 papers, 2011 to 2022). "Similar to BAF250 and BRG-1 depletion, depletion of CHD3 resulted in decreased incidence of latent infections." (PMID 22140357, 2011). "It would be of interest to determine whether these other herpesviruses also use SERBP1 as a scaffold to recruit both KAP1 and CHD3 to their genomes to initiate and maintain a repressive chromatin structure during latent infection." (PMID 36504797, 2022). "We also tested whether similar to BAF, depletion of CHD3 also decreases the incidence of latent infections." (PMID 22140357, 2011). "We now show that the cellular protein Plasminogen activator inhibitor 1 RNA-binding protein (SERBP1), a known interactor of CHD3, is significantly upregulated during HCMV latency and that this protein is required for MIEP suppression during latent infection of myeloid cells." (PMID 36504797, 2022).
lung carcinoma (2 papers, 2019 to 2023). "Notably, S713 phosphorylation in KRAS-mutant A549 lung cancer cells seems to be critical for the stability of CHD3 protein, as S713A mutation dramatically inhibited CHD3 protein expression, whereas the phosphorylation mimicking mutation S173D resulted in increased protein expression." (PMID 36858798, 2023). "CHD3 instead is a member of the NuRD complex, and it also supports viability of KRAS-mutant lung cancer cell lines." (PMID 36858798, 2023).
lung squamous cell cancer (2 papers, 2022). "Similar paradoxical phenomena also existed in lung squamous cell carcinoma, in which CHD1/2 was downregulated and its high expression was associated with poor OS and FP, and in lung adenocarcinoma, in which CHD3 was downregulated, its high expression was linked to poor OS and FP." (PMID 35467222, 2022).
speech disorder (2 papers, 2018 to 2025). A term referring to disorders characterized by the disruption of normal speech. "We describe an index case with a de novo missense mutation in CHD3, identified during whole genome sequencing of a cohort of children with rare speech disorders." (PMID 30397230, 2018). "The mother has a milder phenotype than the child, but she also has a special face, delayed speech development when she was young, and now she has a speech disorder, which is consistent with the variable phenotype and expression of the CHD3 gene." (PMID 40527848, 2025).
Alzheimer disease (1 paper, 2024). A progressive, neurodegenerative disease characterized by loss of function and death of nerve cells in several areas of the brain leading to loss of cognitive function such as memory and language. "One study used an integrated bioinformatics method to identify CHD3 as a hub gene associated with the pathophysiology of Alzheimer’s disease." (PMID 39091293, 2024).
Anxiety (1 paper, 2019). Intense feelings of nervousness, tension, or panic often arise in response to interpersonal stresses. "In line with this, we found that Chd3 is upregulated in proestrus compared to dioestrus females, implying that changing Chd3 levels may contribute to both chromatin reorganization and variation in anxiety behaviour during the oestrous cycle." (PMID 31253786, 2019).
Atherosclerotic lesion (1 paper, 2024). A lesion associated with atherosclerosis, a multifactorial and multipart progressive disease manifested by the focal development within the arterial wall of lesions, that ranges from the development of a fatty streak, plaque progression, and plaque disruption. "CHD3 content was also associated with brachiocephalic lesions at the cut-off 0 (no lesions)/1 (atherosclerotic lesions) (AUC = 0.58; 95% CI (0.51–0.64); p = 0.047)." (PMID 39518432, 2024).
coronary stenosis (1 paper, 2024). Narrowing of the coronary artery lumen diameter. "CHD3 content was associated with coronary stenosis with Gensini score 0/1 as a binary variable defined by ROC analysis: AUC 0.69; 95% CI (0.64–0.75); p = 0.0001." (PMID 39518432, 2024).
diabetes (1 paper, 2025). "These insights underscore the importance of NuRD subunit dynamics in β-cell resilience and suggest that modulating CHD3/4 activity could represent a therapeutic strategy to sustain β-cell function in diabetes." (PMID 41282155, 2025). "Together, our findings establish CHD3 and CHD4 as cooperative guardians of β-cell transcriptional programs and uncover a compensatory mechanism that transiently preserves β-cell resilience under metabolic stress but fails in diabetes progression." (PMID 41282155, 2025).
Glucose intolerance (1 paper, 2025). Glucose intolerance (GI) can be defined as dysglycemia that comprises both prediabetes and diabetes. "Together, these results demonstrate that combined loss of CHD3 and CHD4 compromises β-cell survival and insulin secretory capacity, contributing to the glucose intolerance observed in Chd3/4Δβ mice." (PMID 41282155, 2025). "While β-cell-specific loss of CHD3 alone had little effect, combined deletion of CHD3 and CHD4 caused severe glucose intolerance, impaired insulin secretion, and reduced β-cell area." (PMID 41282155, 2025).
herpes simplex (1 paper, 2023). "CHD3 is involved in chromatin remodeling during development and suppresses herpes simplex virus infection." (PMID 37264206, 2023).
Hypertension (1 paper, 2020). The presence of chronic increased pressure in the systemic arterial system. "However, it is possible that CHD3-NuRD complexes play transcriptional regulatory roles in blood vessels under challenge conditions that were not incorporated into this study, such as ischemia, hypertension, inflammation, glucotoxicity or in solid tumors." (PMID 32658897, 2020).
infantile spasms (1 paper, 2025). A rare epilepsy syndrome characterized by onset of epileptic spasms in infants between 2 and 12 months of age, and rarely up to 24 months. "However, there are no CHD3 gene mutations that have been reported to cause infantile spasms (IS) as yet." (PMID 40527848, 2025).
leukemia (1 paper, 2025). A malignant (clonal) hematologic disorder, involving hematopoietic stem cells and characterized by the presence of primitive or atypical myeloid or lymphoid cells in the bone marrow and the blood. "Although CHD3 has not previously been associated with leukemias, it is a component of the NuRD complex which acts as a chromatin remodeler and is involved in the regulation of numerous downstream targets." (PMID 40832224, 2025).
lung adenocarcinoma (1 paper, 2022). A carcinoma that arises from the lung and is characterized by the presence of malignant glandular epithelial cells. "For example, in lung adenocarcinoma, CHD1/4/6/7/8 was significantly overexpressed, whereas CHD3 was downregulated." (PMID 35467222, 2022).
ocular albinism (1 paper, 2023). Albinism affecting the eye in which pigment of the hair and skin is normal or only slightly diluted. "CHD3 presented with silvery hair, pale skin, and ocular albinism as well as a history of recurrent respiratory and skin infections and nose bleeds." (PMID 36968585, 2023).